GDF11 (growth differentiation factor 11)
Diseases named in the same sentence as GDF11 in open-access papers (continued):
Sharing a sentence is not in itself a finding about the gene and the disease.
osteoporosis (10 papers, 2016 to 2025). A condition of reduced bone mass, with decreased cortical thickness and a decrease in the number and size of the trabeculae of cancellous bone (but normal chemical composition), resulting in increased fracture incidence. "FTO expression resulted in the increase of the serum concentration of GDF11 in the bone, which was a key risk for osteoporosis." (PMID 31998240, 2019). "Increased serum GDF11 concentration was associated with a high prevalence of osteoporosis by stimulating osteoclastogenesis and inhibiting osteoblast through inducing Smad2/3 phosphorylation." (PMID 31998240, 2019). "In addition, rGDF11 treatment impairs bone regeneration in both young and aged mice, and blocking GDF11 function prevents oestrogen-deficiency-induced bone loss and ameliorates age-related osteoporosis." (PMID 27653144, 2016). "Growth differentiation factor 11 (GDF11) is a bone morphological protein (BMP) whose expression is positively correlated with the incidence of osteoporosis in diabetic patients." (PMID 35418946, 2022). "Our data demonstrate that GDF11 is a previously unrecognized regulator of bone remodelling and suggest that GDF11 is a potential target for treatment of osteoporosis." (PMID 27653144, 2016). "Although the results regarding GDF11 are contradictory, it is certain that GDF11 has important roles in age-related diseases, including osteoporosis." (PMID 27408764, 2016). "Is the serum expression of GDF11 low or high in elderly patients with osteoporosis?" (PMID 38143761, 2023). "Similarly, FTO regulated for BMSCs fate determination during osteoporosis through the GDF11-FTO-PPARγ axis, prompting the shift of MSC lineage commitment to adipocyte and inhibiting bone formation during osteoporosis." (PMID 31998240, 2019). "Our data demonstrate that GDF11 is a critical regulator of bone remodelling, and suggest that GDF11 may be a potential target for treatment of osteoporosis." (PMID 27653144, 2016). "However, in elderly patients with osteoporosis, whether GDF11 promotes or inhibits the differentiation of BMSCs into adipocytes is not known." (PMID 38143761, 2023). "Therefore, GDF11 inhibition might be a potential new approach for osteoporosis treatment, especially in patients with high levels of GDF11." (PMID 27653144, 2016). "In fact, FTO is upregulated in bone marrow during aging or osteoporosis in humans and mice in a GDF11 (growth differentiation factor 11)-C/EBPα-dependent mechanism." (PMID 40429638, 2025). "FTO overexpression induces osteogenic differentiation of C3H10T1/2 cells, while the GDF11-FTO-PPARγ axis suppresses bone formation and promotes adipogenic differentiation of osteoporotic bone marrow mesenchymal stem cells during osteoporosis." (PMID 39136019, 2024). "The GDF11-FTO-PPARγ axis prompted the shift of MSC lineage commitment to adipocyte and inhibited bone formation during osteoporosis, as a result of the imbalance between bone mass and fat." (PMID 31998240, 2019). "The GDF11-FTO-PPARgamma axis controls the shift of osteoporotic MSC fate to adipocyte and inhibits bone formation during osteoporosis." (PMID 31998240, 2019).
sarcopenia (10 papers, 2016 to 2026). Progressive decline in muscle mass due to aging which results in decreased functional capacity of muscles. "MR analysis supported a causal protective effect of physical activity on sarcopenia-related traits, while mediation analysis indicated that circulating GDF11 partially mediated this association." (PMID 41822302, 2026). "Multivariable logistic regression identified circulating GDF11 as an independent risk factor for sarcopenia." (PMID 41822302, 2026). "Lower BMI, lower serum ALB, FGF19, TNF-α, and higher circulating GDF11 are associated with sarcopenia." (PMID 40969368, 2025). "The results showed that GDF11 was an risk factor for sarcopenia." (PMID 40969368, 2025). "Although the debate remains lively, GDF11 may regulate age-related muscle loss and be involved in the mechanism by which exercise attenuates sarcopenia." (PMID 31417428, 2019). "Thus, treatment with GDF11 propeptide may be a potential therapeutic strategy for diseases associated with muscle atrophy like sarcopenia and the muscular dystrophies." (PMID 31133057, 2019). "Mendelian randomization (MR) and mediation analyses were conducted to explore potential causal relationships and indirect pathways linking physical activity, circulating GDF11, and sarcopenia." (PMID 41822302, 2026). "Analyses were conducted using binary logistic regression, growth differentiation factor 11(GDF11), was an independent risk factor for sarcopenia [Exp (B) 1.031, 95% CI: 1.010-1.052, p = 0.003]." (PMID 40969368, 2025). "BMI, serum ALB, FGF19, and TNF-α levels were lower in the older adults population with sarcopenia, while GDF11 was higher in the serum of patients with sarcopenia." (PMID 40969368, 2025). "Therefore, elevated GDF11 constitutes an independent predictor of sarcopenia, operating through direct catabolic signaling distinct from GDF15’s metabolic effects." (PMID 40969368, 2025). "Thus, GDF-11 had cardioprotective activities and probably plays a pivotal role in prevention of HF-related myopathy and sarcopenia." (PMID 33520013, 2021). "In this study, we investigated whether the effects of exercise training on sarcopenia involve changes in GDF11 expression in skeletal muscles." (PMID 31417428, 2019). "Given that the administration of recombinant GDF11 improved muscle function, including muscle strength and capacity for endurance exercise, in aged mice, it could be speculated that GDF11 mediates the positive effects of exercise on sarcopenia." (PMID 31417428, 2019). "Compared with circulating factors in non-sarcopenia older adults, FGF19 and GDF11 were significantly higher in sarcopenia older adults." (PMID 40969368, 2025). "However, a previous study has shown that individuals with higher GDF11 are more likely to exhibit frailty, but skeletal muscle mass in that study was not measured and the influence of other factors in the presence of frailty in addition to sarcopenia cannot be discarded." (PMID 30897065, 2019). "Transcriptomic analyses demonstrated that GDF11 mRNA expression in skeletal muscle remained stable regardless of sarcopenia or exercise status, suggesting that elevated circulating GDF11 is unlikely to originate from skeletal muscle." (PMID 41822302, 2026). "In older adults with sarcopenia, serum GDF11 levels were significantly elevated compared to non-sarcopenic controls, while GDF15 showed no statistical difference." (PMID 40969368, 2025). "The serum levels of decorin, BDNF, and GDF-11 were variable and exhibited strong relation to age of the HF patients rather than severity of contractility dysfunction and sarcopenia." (PMID 33520013, 2021). "Because LTBP4 binds GDF11 in vitro, it is possible that muscle specific LTBP4 overexpression could alter sarcopenia or other aging related phenotypes." (PMID 27148972, 2016).
sarcopenia (continued). "Our present results indicate that in SAMP10 mice, sarcopenia can be ameliorated by YBMT via the improvement of protein anabolic responses, the imbalance between muscle apoptosis and proliferation, and mitochondrial biogenesis that are partially mediated by GDF‐11 signalling." (PMID 36058630, 2022).
ischemia (8 papers, 2016 to 2023). A hypoperfusion of the BLOOD through an organ or tissue caused by a PATHOLOGIC CONSTRICTION or obstruction of its BLOOD VESSELS, or an absence of BLOOD CIRCULATION. "Although GDF11 has been suggested to have an antihypertrophic effect in aging mice and patients, the effects of endogenous GDF11 on myocardial ischemia or ischemia/reperfusion (IR) as well as its underlying mechanisms have not been systematically investigated." (PMID 34215721, 2021). "This indicates that the susceptibility of neurons to GDF-11-induced neurotoxicity is during ischemia only, but the effects of this can last during the recovery phase." (PMID 33013673, 2020). "An interesting finding of this study is that circulating GDF11 levels were significantly lower in ACS patients than in CCS patients, suggesting that the role of GDF11 in the heart is dependent on the degree of ischemia." (PMID 34215721, 2021). "Our findings suggest that GDF11 can improve mitochondrial function by preventing ischemia-induced decreases in telomerase activity and TL shortening." (PMID 34215721, 2021). "Our results thus confirm that myostatin and its close homolog GDF11 are differently expressed in the heart in response to ischemia and indicate that they may participate in different processes." (PMID 30765322, 2019). "In our study, GDF11/8 expression increased after kidney ischemia–reperfusion injury (IRI), and the relatively lower level of GDF11/8 in the kidneys of aged mice was associated with a loss of proliferative capacity and a decline in renal repair, compared to young mice." (PMID 27703192, 2016). "However, our evidence suggests that if GDF-11 made it out of the bloodstream and into the brain during ischemia, either through BBB leakage or via some mode of active transport, then it could potentially be harmful to neurons." (PMID 33013673, 2020). "Therefore, in this study, we sought to determine whether GDF-11 administration to primary neurons could provide direct protection to neurons using an in vitro model of ischemia." (PMID 33013673, 2020). "We administered GDF11 at day 5 post-ischemia, by this time; the infarct is fully mature, as we wanted to evaluate the efficacy of GDF11 on brain recovery rather than its potential neuroprotective effects." (PMID 32365331, 2020).
anemia (7 papers, 2016 to 2025). A reduction in the number of red blood cells, the amount of hemoglobin, and/or the volume of packed red blood cells. "GDF11 inhibited human erythropoiesis in vitro and caused anemia in zebrafish, effects that were abrogated by luspatercept." (PMID 40424086, 2025). "Previous studies have shown that GDF11 can lead to mild anemia, and downregulating GDF11 expression can help treat thalassemia." (PMID 38143761, 2023). "Anemia resulting from multiple blood transfusion induced iron accumulation or related to growth differentiation factor-11 (GDF11), GDF15, and hepcidin is one of the characteristics of MDS." (PMID 32344823, 2020). "Over the past 19 years, the role of GDF11 has been investigated in developmental biology and diseases such as anemia and cancer." (PMID 29113418, 2017). "Notably, patient samples of the lower-risk MDS subtypes refractory anemia and refractory anemia with ring sideroblasts, in which anemia is the predominant clinical presentation, have significantly elevated levels of GDF11 and ACVR2B transcripts." (PMID 40424086, 2025). "In anemia, GDF11 promotes proliferation of erythroid precursors and inhibits erythroid maturation." (PMID 29113418, 2017). "Given that GDF11 has been shown to inhibit erythroid maturation in mice, elevation of GDF11 levels may be involved in erythropoietin-resistant anemia in HD patients." (PMID 27298756, 2016). "GDF11 treatment induces anemia in the zebrafish model, which could be rescued by luspatercept." (PMID 40424086, 2025). "This study was cross-sectional and thus could not assess the questions of whether elevation of GDF11 was a cause or consequence of uremia or anemia." (PMID 27298756, 2016). "Our study indicates that GDF11-mediated SMAD2 activation results in an increase in functionally impaired GATA1 isoforms, consequently contributing to anemia and influencing responses to luspatercept in MDS." (PMID 40424086, 2025). "While GDF11 was initially proposed as the major ligand of luspatercept, recent studies showing a lack of anemia improvement in the absence of GDF11 upon ineffective erythropoiesis suggest that other TGF‐β superfamily ligands are the functional targets of luspatercept." (PMID 38434962, 2024).
Cognitive impairment (7 papers, 2015 to 2023). Abnormal cognition is characterized by deficits in thinking, reasoning, or remembering. "The results were statistically analyzed to evaluate the associations between levels of GDF-11 and β2-MG, and ageing and cognitive impairments." (PMID 28611236, 2017). "Thus, the finding that decreased plasma GDF-11 levels were correlated with cognitive impairments in patients with schizophrenia suggests that abnormal GDF-11 signaling is implicated with the pathogenesis of schizophrenia-associated cognitive impairments." (PMID 33364986, 2020). "First of all, although we found that decreased plasma GDF-11 was closely related to the severities of psychopathology and cognitive impairments in schizophrenia patients, the exact mechanism of GDF-11 affecting schizophrenia-related behaviors is not clear." (PMID 33364986, 2020). "Our present findings show a significant decrease in plasma GDF-11 levels in schizophrenia patients, and GDF-11 level was related to the psychopathological symptoms and cognitive impairments." (PMID 33364986, 2020). "It is possible that the accuracy and specificity of measurements in the current study were not sufficient, and future studies are needed to further clarify the biological activities of GDF-11 and β2-MG in ageing and cognitive impairment." (PMID 28611236, 2017). "Recent research has shown that young blood can reverse cognitive impairments and improve cognitive function by regulating related cytokines, such as Growth Differentiation Factor 11 (GDF11) and C-C motif Chemokine 11 (CCL11)." (PMID 26317549, 2015). "Despite increasing reports on the various effects of GDF11, it remains unknown whether GDF11 improves cognitive impairments, as well as its precise mechanism of action in the brain." (PMID 37118117, 2023). "Moreover, little is known regarding the role of GDF-11 or β2-MG in the ageing process and cognitive impairment in the Chinese population." (PMID 28611236, 2017). "Currently, the effects of GDF-11 and β2-MG on ageing and cognitive impairment remain controversial." (PMID 28611236, 2017). "Therefore, we postulate that disrupted GDF-11 signaling results in abnormalities of neurogenesis, astrocyte function and brain activity during early development, leading to the emergence of psychotic symptoms and cognitive disorders in late adolescence and young adulthood." (PMID 33364986, 2020). "We did not detect differences in circulating GDF-11 levels amongst the healthy advanced age and four cognitive impairment advanced age groups." (PMID 28611236, 2017). "We did not detect differences in circulating GDF-11 levels amongst the healthy advanced age and four cognitive impairment groups." (PMID 28611236, 2017). "Collectively, the correlations between plasma GDF-11 and psychopathological and cognitive symptoms suggest that abnormal GDF-11 signaling might contribute to schizophrenic psychopathology and cognitive impairments and GDF-11 could be a potential and promising biomarker for schizophrenia." (PMID 33364986, 2020). "Our results suggest that circulating GDF-11 may not exert a protective effect during the ageing process or on cognitive function, and β2-MG may play a role in ageing and cognitive impairment." (PMID 28611236, 2017).
hepatocellular carcinoma (7 papers, 2019 to 2025). A malignant tumor that arises from hepatocytes. "GDF11 acts as a tumor suppressor in hepatocellular carcinoma (HCC) by inhibiting cell proliferation, migration, and angiogenesis, while promoting apoptosis and autophagy via inactivation of the mTORC1 signaling pathway." (PMID 39315094, 2024). "Similarly, GDF11 also activated non-Smad (e.g., AMPK, MAPK, mTOR, PI3K) pathways in a wide range of cell types, such as cardiomyocytes, neural stem cells, human hepatocellular carcinoma cells, primary hepatocytes, and mesenchymal stem cells." (PMID 36293138, 2022). "Growth differentiation factor 11 (GDF11) is a secreted protein in the TGF-β superfamily and the BMP subfamily and exerts tumor-suppressive function in a variety of many cancers, such as triple-negative breast cancer, pancreatic cancer, and hepatocellular carcinoma." (PMID 35978818, 2022).
Insulin resistance (7 papers, 2018 to 2024). Increased resistance towards insulin, that is, diminished effectiveness of insulin in reducing blood glucose levels. "GDF11 can alleviate a series of symptoms caused by a high-fat diet, such as weight gain, hyperglycemia disorder, insulin resistance, and increased white fat production." (PMID 36755591, 2023). "In obese mice, GDF11 ameliorates fatty liver by improving glucose intolerance and insulin resistance, leading to reduced hepatic steatosis." (PMID 39872377, 2024). "Based on our in vitro data, we offer another explanation of how GDF11 can counteract insulin resistance and ameliorate diabetic symptoms." (PMID 35920128, 2022). "ITT assay showed a higher response to injected insulin, and HOMA-IR showed a decrease in insulin resistance in GDF11 treated mice." (PMID 31847906, 2019). "In obese and STZ-induced diabetic mice, Gdf11 gene transfer restores glucose metabolism and improves insulin resistance." (PMID 31847906, 2019). "HOMA-IR confirmed that Gdf11 gene transfer suppressed the development of insulin resistance." (PMID 31847906, 2019). "Sustained expression of the Gdf11 gene induces AMPK activity, which is important in glucose uptake and homeostasis, and thus improves insulin resistance and glucose intolerance induced by HFD." (PMID 39872377, 2024). "It has been reported that incubation with GDF11 does not ameliorate palmitate-induced insulin resistance in murine myotubes." (PMID 30897065, 2019). "However, the GDF11 did not ameliorate the palmitate-induced insulin resistance and GDF11 treatment did not change expression of Glut4 or Irs-1." (PMID 31681577, 2019). "However, GDF11 has not been shown to be related to the enhancement of insulin resistance induced by palmitate in a skeletal muscle cell line or to lifespan in a premature elderly animal model." (PMID 29783655, 2018).
ischemic heart disease (7 papers, 2017 to 2022). "It was demonstrated, in patients with stable ischemic heart disease, that higher GDF11/8 levels were associated with a lower risk of cardiovascular events and death, suggesting cardioprotective properties of GDF11/8." (PMID 30545044, 2018). "However, in patients with ischemic heart disease, higher plasma levels of GDF11 have been associated with lower risk of cardiovascular events and death, indicating that GDF11 is more likely associated with cardiovascular risk than with aging." (PMID 36077021, 2022). "In patients with coronary artery disease, whole blood GDF11 and SIRT1 expression levels were strongly correlated." (PMID 34262905, 2021).
liver cancer (7 papers, 2019 to 2025). An epithelial or non-epithelial malignant neoplasm that arises from the liver. "This study sheds light on the crucial role of GDF11 in liver development and pathophysiology of associated liver diseases including liver cancers and MAFLD." (PMID 38494851, 2024). "In liver cancer, pancreatic cancer, esophageal cancer, and cholangiocarcinoma, the expression of GDF11 is downregulated." (PMID 38143761, 2023). "In hepatic tumorigenesis, GDF11 was reported to reduce the viability of liver cancer cells and its mRNA expression was down-regulated in tumor tissues compared with that in the matching normal tissues." (PMID 32050622, 2020). "GDF11 also induced a decrease in number and size of the spheroids and generated more-compacted structures by the increment in E-cadherin, as observed in liver cancer cell lines, and GDF11 treatment induces a cell-cell adhesion preventing metastasis phenomena." (PMID 31681577, 2019). "The PI3K-AKT pathways are responsible for GDF11-induced lipid accumulation in liver cancer cells." (PMID 38844980, 2024).